DEPTOR (DEP domain containing MTOR interacting protein)
Description:
Negative regulator of the mTORC1 and mTORC2 complexes: inhibits the protein kinase activity of MTOR, thereby inactivating both complexes. DEPTOR inhibits mTORC1 and mTORC2 to induce autophagy. In contrast to AKT1S1/PRAS40, only partially inhibits mTORC1 activity.
Synonyms: hDEPTOR; DEPDC6; DEP.6; FLJ12428
Tractability: Small molecule: a high-quality ligand is known. Antibody: its Gene Ontology location is reachable by antibodies, with medium confidence. PROTAC: UniProt records ubiquitination sites on it; ubiquitination databases record sites on it; a small molecule that binds it is known.
Gene: Protein-coding gene on chromosome 8 (119,873,717 to 120,050,918, forward strand). Ensembl gene ENSG00000155792.
Subcellular location: Lysosome membrane
Subcellular location (Human Protein Atlas): Mitochondria; Nuclear bodies; Nucleoplasm
Gene Ontology:
Molecular function: phosphatidic acid binding; protein binding; protein kinase inhibitor activity; protein serine/threonine kinase inhibitor activity; GTPase activator activity; guanyl-nucleotide exchange factor activity
Biological process: negative regulation of cell size; negative regulation of protein kinase activity; negative regulation of TOR signaling; negative regulation of TORC1 signaling; negative regulation of TORC2 signaling; positive regulation of autophagy; regulation of extrinsic apoptotic signaling pathway; G protein-coupled receptor signaling pathway; intracellular signal transduction
Cellular component: lysosomal membrane; plasma membrane
Genetic constraint (gnomAD): Loss-of-function variants: 39 observed, 40.97 expected, observed/expected ratio (o/e) 0.95, 90% interval 0.74 to 1.24. The upper end of that interval is the gene's LOEUF score, 1.24, which puts it in group 5 of 6, group 1 being the genes least tolerant of losing a copy. Missense variants: 486 observed, 523.36 expected, observed/expected ratio (o/e) 0.93, 90% interval 0.86 to 1. Synonymous variants: 183 observed, 189.3 expected, observed/expected ratio (o/e) 0.97, 90% interval 0.86 to 1.09.
Homologues: Orthologues: chimpanzee DEPTOR (100% identical), macaque DEPTOR (99% identical), dog DEPTOR (99% identical), pig DEPTOR (99% identical), rabbit DEPTOR (99% identical), mouse Deptor (96% identical), rat Deptor (89% identical), guinea pig DEPTOR (85% identical), tropical clawed frog deptor (77% identical), zebrafish deptor (76% identical). Paralogues in human: PREX1 (33% identical), PREX2 (33% identical), GPR155 (15% identical).
Diseases named in the same sentence as DEPTOR in open-access papers:
DEPTOR is named in the same sentence as 84 diseases in open-access papers, as found by Europe PMC text mining. Sharing a sentence is not in itself a finding about the gene and the disease. The quoted sentences say what the papers report.
multiple myeloma (24 papers, 2012 to 2025). "It has been shown that DEPTOR is necessary for myeloma differentiation and that higher levels are linked to improved outcomes." (PMID 36224246, 2022). "The ectopic expression of miR-135b and miR-642a in myeloma cell lines substantially diminished DEPTOR protein levels, and caused dedifferentiation of myeloma cells." (PMID 28420429, 2017). "The differences in DEPTOR protein expression among MM patients led us to hypothesize that DEPTOR levels might be associated with the maturation state of myeloma cells of each patient, in line with our results from MMCLs." (PMID 28420429, 2017). "DEPTOR was shown to be an oncogene in hepatocellular carcinoma, ERα-negative breast cancer and esophageal squamous cell carcinoma, multiple myeloma and differentiated thyroid cancer, possibly through a"feedback model"mechanism." (PMID 40650680, 2025). "For instance, DEPTOR is highly expressed in prostate cancer and multiple myeloma and promotes tumor survival by activating the PI3K/Akt signaling pathway but is less expressed in hepatocellular and colorectal cancers and adipocytes." (PMID 41249115, 2025). "Downregulation of DEPTOR has been shown to induce apoptosis and increase sensitivity to doxorubicin in human multiple myeloma cells." (PMID 37756103, 2023). "This trend has been documented for DEPTOR, with low expression of the gene observed in most cancers, yet high overexpression seen in a group of multiple myelomas." (PMID 34197603, 2021). "It has been shown that DEPTOR is overexpressed in multiple myeloma cells and is required for cell survival." (PMID 33995662, 2021). "In mature myeloma cells, DEPTOR (DEP domain containing MTOR interacting protein) increases sensitivity to therapeutic agents by inhibiting the activity of mTOR kinases." (PMID 35095893, 2021). "DEPTOR is highly overexpressed in Multiple Myeloma cells, which protects these cells from apoptosis." (PMID 34519269, 2021). "DEPTOR is a direct endogenous inhibitor of mTORC1 and mTORC2 that is overexpressed in various cancers, such as colorectal cancer, osteosarcoma, myeloma, cervical squamous cell carcinoma and HCC." (PMID 31228948, 2019). "In multiple myeloma, DEPTOR maintains differentiation, and its high expression predicts a better prognosis." (PMID 31228948, 2019). "Our results demonstrate for the first time that DEPTOR expression is required to maintain myeloma cell differentiation and that high level of its expression are associated with better outcome." (PMID 28420429, 2017). "Consistent with the mRNA expression data, we observed that levels of DEPTOR protein also differed among the myeloma samples." (PMID 28420429, 2017). "Using luciferase reporter assays and gain-of-function experiments, we showed that transfection of miR135b and miR642a decreased DEPTOR levels in myeloma cells." (PMID 28420429, 2017). "We observed that DEPTOR downregulation induced by miR135b and miR642a ectopic expression also reverted the transcriptional program of the myeloma cells and reduced cell size and ER mass, similarly to the results obtained from DEPTOR silencing by siRNA." (PMID 28420429, 2017). "Here, we explore the role of DEPTOR, an mTOR inhibitor, in the terminal differentiation of myeloma cells, and its potential impact on patient survival." (PMID 28420429, 2017). "Just like in multiple myeloma, one study reported that mTORC1 and mTORC2 inhibitors inhibit tumor growth, including DEPTOR, whereas another study revealed that DEPTOR silence induces cytoreductive effects on multiple myeloma (MM) cells." (PMID 26893358, 2016). "We investigated the mechanism by which gene silencing of the mTOR inhibitor, DEPTOR, induces cytoreductive effects on multiple myeloma (MM) cells." (PMID 25568666, 2014). "DEPTOR is a 48 kDa protein upregulated in multiple myeloma (MM) cells." (PMID 35216969, 2022). "Thus, myeloma-specific upregulation of DEPTOR expression provides a key step to maintaining cell viability during tumor clonal expansion." (PMID 35216969, 2022).
multiple myeloma (continued). "Exceptions are a subset of multiple myeloma (MM), thyroid carcinoma, and lung cancers, where overexpression of DEPTOR eliminates feedback inhibition downstream of mTORC1, resulting in hyperactivation of PI3K/mTORC2/Akt signaling and thereby stimulating cell survival." (PMID 34519269, 2021). "Paradoxically, DEPTOR acts as a tumor suppressor in lung adenocarcinoma and multiple myeloma." (PMID 31228948, 2019). "We demonstrated that PGG inhibited the MYC and DEPTOR expression in myeloma cells." (PMID 29472861, 2018). "Next, we analyzed the effect of DEPTOR downregulation on myeloma cell morphology." (PMID 28420429, 2017). "Interestingly, the level of expression of DEPTOR protein in myeloma patients was highly variable, the highest levels being associated with longer progression-free survival." (PMID 28420429, 2017). "Furthermore, the antitumor activity of DEPTOR has been confirmed in colorectal cancer, liver cancer, multiple myeloma and pancreatic cancer." (PMID 26893358, 2016). "Thus, DEPTOR expression has frequently been reported to be essential for the survival and proliferation of tumor cells in multiple myeloma, thyroid cancer, paclitaxel resistant ovarian cancer and hepatocellular carcinoma." (PMID 26992219, 2016). "However, DEPTOR was also reported to have an oncogenic role and found to be overexpressed in many cancers such as multiple myeloma, paclitaxel resistant ovarian cancer, hepatocellular carcinoma and thyroid cancer." (PMID 26992219, 2016). "The highest levels of DEPTOR mRNA are found in specific genetic categories of multiple myeloma." (PMID 25568666, 2014). "Targeting DEPTOR, possibly in combination with proteasome inhibition, might thus be a promising therapeutic strategy for this subset of patients with DEPTOR-high bortezomib-resistant myeloma." (PMID 37081258, 2023). "DEPTOR, which we identify as top negative association to bortezomib sensitivity, could be an upstream master regulator of this cellular state in myeloma." (PMID 37081258, 2023). "However, in some other cancers, e.g., multiple myeloma, DEPTOR expression is elevated." (PMID 35078427, 2022). "However, DEPTOR is surprisingly strongly expressed in some cancers, including multiple myeloma." (PMID 29670094, 2018). "However, the function of DEPTOR in tumorigenesis is still controversial, as DEPTOR has also been found to be overexpressed in many other tumor types including breast cancer, chronic myeloid leukemia and multiple myeloma." (PMID 26893358, 2016). "However, in a subset of multiple myeloma cells, where DEPTOR was overexpressed, DEPTOR acts as an oncogene and survival factor, since DEPTOR inhibition of mTORC1 relieves the feedback inhibition from S6K1 to PI3K, boosting AKT activity for cancer cells survival." (PMID 25544749, 2014). "Importantly, as DEPTOR is strongly expressed in some cancers, including multiple myeloma, clinical suppression of DEPTOR expression or activity, or its downstream signaling pathway, may achieve the best combination for prevention of cisplatin-induced injury and cisplatin antitumor efficacy." (PMID 29670094, 2018). "DEPTOR knockdown in H929 and MM1S cell lines induced dedifferentiation of myeloma cells, as demonstrated by the upregulation of PAX5 and BCL6, the downregulation of IRF4, and a clear reduction in cell size and endoplasmic reticulum mass." (PMID 28420429, 2017). "In order to confirm the previously observed overexpression of DEPTOR by microarray analysis in NPC and myeloma cells relative to NBL (GSE6691 at GEO repository), we quantified DEPTOR mRNA levels by qRT-PCR in four BC populations." (PMID 28420429, 2017). "Consistency with the multifaceted nature of most aspects of cancer, DEPTOR has been reported to be overexpressed in multiple myeloma cells, which suggests a role of oncogene rather than tumor suppressor." (PMID 35078427, 2022).
breast carcinoma (13 papers, 2012 to 2025). "We have recently found that MLN4924 effectively induced autophagy in breast cancer cell lines via causing accumulation of HIF1α and DEPTOR to inactivate mTORC121." (PMID 27063292, 2016). "Our study also showed that DEPTOR is indispensable for the proliferation and survival of ErbB2-positive breast cancer cells." (PMID 33995662, 2021). "It has been shown that DEPTOR expression is decreased in aggressive breast cancers, and paradoxically, it inhibits breast cancer growth and invasion." (PMID 33995662, 2021). "The mRNA level of DEPTOR was significantly decreased in breast cancer tissues compared to that in normal breast tissues (p < 0.001)." (PMID 33995662, 2021). "In summary, our study uncovered a crucial interplay between DEPTOR and ErbB2 in the regulation of cell proliferation and survival in ErbB2-positive breast cancer cells." (PMID 33995662, 2021). "Next, we determined the potential mechanisms by which DEPTOR facilitates the development of human breast cancer." (PMID 33995662, 2021). "The decrease in S6K1 and AKT phosphorylation upon DEPTOR silencing suggested that the reduction in the levels of ErbB2 by DEPTOR knockdown appears to play a major role in suppressing the PI3K/AKT/mTOR pathway in ErbB2-positive breast cancer cells." (PMID 33995662, 2021). "To explore the localization of DEPTOR in breast cancer cells, we first examined the specificity of DEPTOR antibody in an IF assay using BT474 cells transfected with siRNA targeting DEPTOR (siDEPTOR)." (PMID 33995662, 2021). "In this study, we found that in ErbB2-positive breast cancer tissues and cells, DEPTOR is present on the cell membrane where it interacts with ErbB2 (residues 1026 to 1240) via its PDZ domain." (PMID 33995662, 2021). "DEPTOR has been found to be overexpressed in many tumor types, including breast cancer, prostate cancer, chronic myeloid leukemia, lung cancer, and MM." (PMID 28420429, 2017). "The role of DEPTOR as a tumor suppressor is consistent with its low expression revealed in a number of human cancers, including pancreas, esophageal squamous cell carcinoma, lungs, and breast cancer." (PMID 35078427, 2022). "Importantly, DEPTOR expression is increased in human breast cancer tissues and its overexpression correlates with poor patient survival." (PMID 33995662, 2021). "In this study, we demonstrated that DEPTOR functions as a positive regulator of ErbB2 in ErbB2-positive breast cancer cells, which may contribute to the development of human breast cancer." (PMID 33995662, 2021). "Previous studies have shown that DEPTOR levels are reduced in metastatic cancer cells (e.g., endometrial cancer tissues and breast cancer cells), and DEPTOR reduction or depletion promotes EMT (epithelial–mesenchymal transition), whereas its overexpression represses this process." (PMID 31685947, 2020). "However, to our knowledge, this study is the first to demonstrate that exposure of epithelial breast cancer cells to medium collected from contracting skeletal muscles results in a rescue of DEPTOR within the cancer cell, blunting mTOR signaling and with consequent reductions in protein synthesis." (PMID 36388131, 2022). "Taken together, DEPTOR expression is increased in human breast cancer tissues and may serve as a biomarker for the prognosis of breast cancer patients, suggesting that the increase in DEPTOR expression might play a role in the development of human breast cancer." (PMID 33995662, 2021). "However, the relationship between DEPTOR and metastasis has only been reported in breast cancer." (PMID 31228948, 2019). "However, DEPTOR partially suppresses the EMT in breast cancer cells." (PMID 31228948, 2019). "However, whether DEPTOR regulates the growth of ErbB2-positive breast cancer cells remains unknown." (PMID 33995662, 2021).
breast carcinoma (continued). "Interestingly, the fusion genes identified by analyzing breast cancer genome rearrangements indicated that ErbB2 might serve as an adaptor for DEPTOR in regulating the mTOR pathway 25, thus adding another layer of complexity in the cross-talk between DEPTOR and ErbB2 in breast tumorigenesis." (PMID 33995662, 2021). "Taken together, our results suggest that DEPTOR knockdown suppresses cell proliferation and survival by inactivating the PI3K/AKT/mTOR pathway to induce apoptosis in ErbB2-positive breast cancer cells." (PMID 33995662, 2021). "The knockdown of RPS27L induces autophagy in breast cancer MB231 and SK-BR3 cells by shortening the protein half-life of β-TrCP which is involved in the degradation of DEPTOR, the natural inhibitor of mTOR." (PMID 34873618, 2021). "DEPTOR is overexpressed and promotes cancer cell proliferation and survival by feedback activation of the PI3K/AKT pathway in various cancers including cervical squamous cell carcinoma, osteosarcoma, breast cancer, colorectal cancer and HCC." (PMID 31228948, 2019). "This is, however, not mediated by accumulated HIF1α and DEPTOR, as seen in breast cancer cells." (PMID 27063292, 2016). "In breast cancer, studies showed that DEPTOR expression is repressed by EMT programs in estrogen receptor α negative cells, and also decreased in cancer stem cells or tumor tissues of patients with aggressive breast cancers, however it is essential for the growth and Chemo-resistance of tumor cells." (PMID 26893358, 2016). "Several of the genes involved are also in signalling pathways relevant to breast cancer: ERBB2, NRIP1 and BCAS3 are involved in estrogen receptor function and APPBP2 with androgen receptor; while TAOK1 and SKAP1 are involved in MAPK signalling and DEPDC6/DEPTOR regulates mTOR signalling." (PMID 23260012, 2012).